NOX1 (NADPH oxidase 1)
Diseases named in the same sentence as NOX1 in open-access papers (continued):
Sharing a sentence is not in itself a finding about the gene and the disease.
lung carcinoma (9 papers, 2013 to 2024). "Liu and colleagues revealed a greater expression of NOX1 according to tumor progression in lung cancer." (PMID 38542437, 2024). "Combing these results suggested that TLR4 activation in response to LPS led to enforced NADPH oxidase 1 activity, which in turn increased ROS production and human lung cancer progression." (PMID 27286259, 2016). "NADPH oxidase 1-dependent ROS was crucial for TLR4 signaling triggered tumor metastasis of human lung cancer." (PMID 27286259, 2016). "Real-time RT-PCR results indicate that Nox1, 2 and 5 are abundantly expressed in both A549 and H460 cells, whereas Nox 3 and 4 are barely detectable in lung cancer cells." (PMID 23533664, 2013). "NOX1 plays an important role in ROS generation and lung cancer." (PMID 35866375, 2022).
breast carcinoma (8 papers, 2012 to 2025). "Our present experiments show that an AWP1 deficiency induces EMT gene expression and breast cancer cell migration, indicative of an aggressive tumor phenotype, which is mediated by Nox1-ROS-NF-κB-linked signal activation via TNF-α stimulation." (PMID 33816268, 2021). "Our current study findings have revealed that AWP1 plays a crucial role in the TNF-α-induced migration of breast cancer cells by showing that the ‘Nox1-ROS–NF-κB–EMT-related genes’ cascade can be potentially regulated by AWP1." (PMID 33816268, 2021). "We found that the Nox1 and Nox5 mRNA levels of AWP1 KO breast cancer cell lines were significantly higher than those of WT cells and these enhancement of Nox1 and 5 were further induced by TNF-α exposure." (PMID 33816268, 2021). "Further, Memo is important for the sustained production of the reactive oxygen species O2− by NADPH Oxidase 1 (NOX1) in breast cancer cells." (PMID 34988012, 2021). "Among the NOX family members, NOX1, in particular, has been responsible for elevated ROS levels in 80% of all human breast cancers." (PMID 27418140, 2016). "The present data show that the generation of ROS is responsible for cambogin-induced interaction of p22phox and NOX1 in breast cancer cell membranes both in vitro and in vivo." (PMID 27418140, 2016). "We also demonstrated that the activation of ASK1 lies downstream of NOX1-derived ROS production in cambogin-treated breast cancer cells." (PMID 27418140, 2016). "Less than 5% of patients with prostate, ovary, lung, or breast carcinoma were high NOX1 expressers." (PMID 32428030, 2020). "Therefore, all our data combined indicate that breast cancer progression can be effectively prevented by targeting the ROS/NOX1-dependent signaling transduction pathway, potentially providing several therapeutic targets for breast cancer treatment." (PMID 27418140, 2016). "Our findings support the notion that there is a direct link between NOX1 and ASK1 which plays an important role in mediating breast cancer cell viability." (PMID 27418140, 2016). "Notably, the inhibition of NOX1 was sufficient to prevent the dissociation of Trx1 from ASK1 and hence the activation of ASK1/JNK, implying that targeting this pathway is likely to be a promising strategy for the treatment of breast cancer." (PMID 27418140, 2016).
Sepsis (8 papers, 2015 to 2024). Sepsis is defined as life-threatening organ dysfunction caused by a dysregulated host response to infection. "As revealed by these results, the induction of NLRP3 inflammasome through GPR43 inhibition-caused mitochondrial damage by NOX-1 was dominant in determining sepsis-induced inflammatory reactions." (PMID 34584017, 2021). "In this study, EBP50/Nox1/p47phox is involved in the activation of NLRP3 Inflammasome in sepsis model by the inhibition of GPR43 via PPARγ." (PMID 34584017, 2021). "To conclude, GPR43 is involved in the inactivation of NLRP3 inflammasome in sepsis model by ROS-induced mitochondrial damage via PPARγ/ EBP50/Nox1/p47phox." (PMID 34584017, 2021). "Together with previous findings, our results indicate that GRP43 alleviated mitochondrial damage in macrophage by the promotion of ROS production to alleviate NLRP3 inflammasome of sepsis model by PPARγ/ Nox1/ EBP50/p47phox signaling." (PMID 34584017, 2021). "Although expression of Nox1 is relatively low in heart compared to Nox2 and Nox4, sepsis-induced myocardial cell death and ROS production were significantly suppressed in Nox1-deficient mice." (PMID 28936433, 2017). "Notably, this study showed that GPR43 induced PAK4 and PPARγ protein expressions and suppressed Nox1 protein expression in macrophage by LPS+ATP or mice model of sepsis." (PMID 34584017, 2021). "Moreover, CLP- and endotoxin-induced sepsis enhanced the mRNA expression of NADPH oxidase Nox1 in vivo, also leading to increased production of ROS." (PMID 32410859, 2020). "Among all sepsis groups, the L group had higher PGC-1α expression, whereas the L and GL groups had higher expression levels of NOX1 on day 4 after CLP." (PMID 34884807, 2021). "Others reported that NOX1 contributes to cardiomyocyte apoptosis and ventricular systolic dysfunction while NOX4 mediates renal tubular inflammation, apoptosis and mitochondrial dysfunction in sepsis." (PMID 38966542, 2024).
inflammatory bowel disease (7 papers, 2017 to 2024). A spectrum of small and large bowel inflammatory diseases of unknown etiology. "This corroborates with clinical observations that loss-of-function mutations of NOX1 could be attributable for the development of inflammatory bowel disease." (PMID 37134122, 2023). "NADPH oxidase 1 (NOX1), which is an important regulator of mucosal immunity, is dysregulated during inflammatory bowel disease." (PMID 35997395, 2022). "In humans, loss-of-function variants of Nox1 may not cause a disease, but represent context-specific modifiers that may worsen an inflammatory bowel disease." (PMID 32164269, 2020). "Literature data showed that NOX1 and DUOX2 have significant roles in Helicobacter pylori-induced gastric inflammation, inflammatory bowel disease (IBD), and tumors." (PMID 33573222, 2021).
cardiac hypertrophy (6 papers, 2010 to 2025). "These cells produce various proinflammatory cytokines and ROS that activates multiple signaling pathways (CaNA/STAT3, TGF-β1/Smad2/3, IKKɑ/NF-kB, and NOX1/4), thereby leading to cardiac hypertrophy, fibrosis, inflammation and DNA damage (cardiac remodeling)." (PMID 36467095, 2022). "In the present study, Ang II was found to induce myocardial hypertrophy, fibrosis, oxidative stress, and inflammation, as evidenced by alterations in the PI3K/AKT1/mTOR/ERK, TGF-β/Smad2/3, NF-κB, and NOX1 signaling pathways." (PMID 39715792, 2025). "We studied therefore the effect of angiotensin II-induced early cardiac hypertrophy on the three major NOX enzymes present in the heart, NOX1, NOX2 (or gp91-phox) and NOX4." (PMID 21151982, 2010).
myocardial infarct (6 papers, 2020 to 2024). "NOX1 elevation risks myocardial injury and myocardial infarction by inducing oxidative stress and inflammation." (PMID 35918636, 2022). "Systemic Nox1, Nox2, and Nox1/Nox2 double KO mice were shown to exhibit a significant decrease in myocardial infarct size after I/R, but systemic Nox4 KO mice did not." (PMID 35739967, 2022). "NOX1, NOX2, NOX4, and NOX5 are expressed in the vascular wall and are related to different cardiovascular diseases (CVDs), such as atherosclerosis, hypertension, heart failure, or myocardial infarction (MI)." (PMID 32155782, 2020). "Systemic NOX1, NOX2, and NOX1/NOX2 double KO mice showed a significant reduction in myocardial infarct size following I/R, while systemic NOX4 KO mice did not." (PMID 36770715, 2023).
type 2 diabetes (6 papers, 2020 to 2024). "A large amount of oxidative stress occurs in patients with type 2 diabetes, resulting in complications, and the increase in oxidants comes from mitochondria that are not functioning and NOX1 (NADPH oxidase 1) in the liver." (PMID 36624538, 2023). "However, a clinical trial outcome in patients with type 2 diabetes and kidney disease by Genkyotex using a dual NOX1/4 inhibitor, GKT137831, was negative as the inhibitor was unable to reduce albuminuria, which was the primary endpoint." (PMID 38671844, 2024). "Importantly, GSK137831, an inhibitor of Nox1/4, has been passed through Phase 1 clinical trials (NCT02010242) for treatment of Type 2 Diabetes and Albuminuria, suggesting that GSK137831 may be used in the clinical treatment of activated osteoclastogenesis disease." (PMID 34650437, 2021).
bladder cancer (5 papers, 2011 to 2024). "For example, the silencing of ALKBH8, a member of the human AlkB family of DNA repair molecules, leads to a decrease in ROS production, via the downregulation of NOX1 in urothelial cancer and to apoptosis resistance, resulting in bladder cancer development." (PMID 29065504, 2017). "NOX1 protein expression is higher in high-grade and invasive disease than in low-grade and non-invasive disease, in human bladder cancer tissues." (PMID 29065504, 2017). "Several researches indicate that the decrease in NOX1 expression in urothelial carcinoma results in a decline in the generation of reactive oxygen species (ROS) and a resistance to programmed cell death, ultimately contributing to the progression of bladder cancer." (PMID 38305808, 2024). "In addition to NOX4, NOX1-mediated enhancement of ROS generation might result in bladder cancer cells of a more aggressive phenotype." (PMID 22032647, 2011). "In addition, other reports have shown that the knockdown of NOX1 reduces ROS production and apoptosis by FK228, a histone deacetylase inhibitor, in a human bladder cancer cell line (J82 cells)." (PMID 29065504, 2017).
Cerebral ischemia (5 papers, 2013 to 2022). Restriction of arterial blood supply to the brain associated with insufficient oxygenation to support the metabolic requirements of the tissue. "The contribution of isoform Nox1 to BBB permeability induced by cerebral ischemia has also been demonstrated." (PMID 36290688, 2022). "Upregulation of Nox1, Nox 4, and Nox5 occurs during brain endothelial aging, cerebral ischemia, and in the AD brain." (PMID 35813502, 2022). "It was shown that in vivo Nox1 depletion reduces neurological deficits, lesion volume and BBB disruption in a cerebral ischemia model induced by tMCAO." (PMID 36290688, 2022). "There are, however, relatively few studies of the role of Nox1 in brain endothelial permeability and BBB dysfunction and the role of Nox1 in cerebral ischemia is still controversial." (PMID 36290688, 2022). "Of these NOX isoforms identified hitherto, NOX1, NOX2, and NOX4 are expressed in the brain and involved in BBB dysfunction after cerebral ischemia and reperfusion." (PMID 28690765, 2017). "We found that Nox1 knockdown improved the survival and differentiation of progenitor cells in the SVZ after cerebral ischemia." (PMID 25617620, 2015). "However, a lack of Nox1 was found not to confer protection in transient or permanent cerebral ischemia." (PMID 25617620, 2015).
colon adenocarcinoma (5 papers, 2015 to 2023). "We compared the mutations of the NOX1 genes from IBD and colon adenocarcinoma patients with the key binding residues identified in our docking analysis using the NOX1 structural model." (PMID 37134122, 2023). "In colon adenocarcinoma cells NOX1 was shown to act as a switch between random and directional migration and to control the directionality of cell migration." (PMID 25806803, 2015). "NOX1 is primarily found in normal colonic epithelium; to date, expression of NOX1 has also been shown to be increased in small series of tissue specimens from patients with pre-malignant chronic inflammation of the colon and small intestine, as well as in patients with colon adenocarcinomas." (PMID 32428030, 2020).
coronary artery disease (5 papers, 2017 to 2022). "NOX1 and NOX2 activity enhanced in the coronary arteries from patients with coronary artery disease, whereas there seems a critical role of oxidative stress caused by NOX2 and NOX4 in the progression of heart failure." (PMID 34440716, 2021). "Our study thus added new evidence that transcriptional regulation of NOX1 are involved in ox-LDL induced ROS production and cell migration in vascular cells, suggestingNOX1might be targeted for the purpose of treating coronary diseases." (PMID 32513988, 2020).
COVID-19 (5 papers, 2021 to 2025). A disease caused by infection with severe acute respiratory syndrome coronavirus 2. "Evidence has been accumulating that COVID-19 is a multi-systemic inflammation posing greatest threats to epithelial and endothelial tissues, where NOX1 is enriched." (PMID 37134122, 2023). "Furthermore, it inhibits NF-κB expression and downregulates NADPH oxidase-1 (NOX-1) and -2, thereby reducing hyperactivated inflammatory pathways in COVID-19." (PMID 39860053, 2025). "Under the current COVID-19 pandemic, therapeutics inhibiting NOX1 activity may be protective against acute lung injury and acute respiratory distress syndrome, which are common complications in severe patients of COVID-19." (PMID 37134122, 2023). "NOX1 may hence be a potential drug target against COVID-19 for its severe symptoms." (PMID 37134122, 2023). "Large infiltrates by Arginase 1+ G-MDSC (Arg+G-MDSC), expressing NOX-1 and NOX-2 (important for production of reactive oxygen species) were found in the lungs of patients who died from COVID-19 complications." (PMID 34341659, 2021). "We highlight the importance of the Ang II/AT1R/NOX1/2 axis-mediated ROS burst in the uncontrolled inflammatory response in SARS-CoV-2 spike RBD protein-induced ALI and suggest that rACE2 can be applied to the clinical treatment of COVID-19 alone or combined with other antiviral agents." (PMID 35681221, 2022). "The expression of Prostaglandin-endoperoxide synthase 2 (PTGS2, also known as cyclooxygenase 2) mRNA was increased in PBMC of mild, but not severe COVID-19 patients, whereas the expression of NADPH oxidase (NOX-1) mRNA was reduced in both mild and severe COVID-19 patients compared to healthy donors." (PMID 33692788, 2021).
depression (5 papers, 2020 to 2023). "Oxidative stress caused by a p47phox-dependent NOX1 or NOX2 seems to impair the microvascular smooth muscle function in depressive disorder." (PMID 34440716, 2021). "Nox1 has been reported to be up-regulated in the ventral tegmental area of the brain in association with depression-like behaviors." (PMID 33613190, 2020). "In the context of pro-oxidant insult, NOX1 upregulation and increased DNA oxidative damage were reported herein (the hippocampal spike of 8-OHdG) and in previous models of stress-induced depression." (PMID 37375795, 2023). "In perspective, NOX1 genetic ablation ameliorated the depressive-like behavioral hallmarks in rodent models of chronic social defeat stress and corticosterone-evoked depression." (PMID 37375795, 2023). "Our data suggested that geniposide could potentially alleviate the depression-like behaviors in mice by decreasing the Nox1 through enhancing the expression of miR-298-5p." (PMID 33613190, 2020). "Therefore, we designed this study to explore the correlation between geniposide, miR-298-5p, and Nox1 in depression." (PMID 33613190, 2020). "Hence, this study revealed an antidepressant effect of geniposide on CUMS-induced depression-like behavior in mice by down-regulating the miR-298-5p-targeted Nox1." (PMID 33613190, 2020). "Of note, therapeutic strategies that target NOX1 and NOX4 downregulation have been envisioned as successful tools for the attenuation of depression and other neurodegenerative diseases." (PMID 37375795, 2023). "Together, the present findings prove the neuroprotective/antidepressant actions of meloxicam in CRS-induced depression by ameliorating hippocampal neuroinflammation and pro-oxidant changes, likely by modulating COX-2/NOX1/NOX4/Nrf2 axis." (PMID 37375795, 2023). "Nox1-induced ROS in the prefrontal cortex downregulated the level of BDNF, promoting depression in mice." (PMID 35850611, 2022). "Nox1 is a non-phagocytic form of 2, 4-dienoyl-CoA reductase 1 (NADPH) oxidase that plays a crucial role in depression-like behaviors." (PMID 33613190, 2020).
lung injury (5 papers, 2012 to 2024). "NOX1 has been reported to worsen hyperoxia-induced acute lung injury in mice, and NOX4 has been suggested to stimulate microglial IL-6 expression and to hamper neurodegeneration after poststroke ischemia reperfusion injury." (PMID 22529530, 2012). "In mice, GKT137831 ameliorated hypertensive cardiac remodeling, doxorubicin-induced cardiotoxicity, acute lung injury, acute kidney injury, and type I diabetes vascular dysfunction, the effects of which were attributed to inhibition of NOX1/4-driven ROS production in vivo." (PMID 36670953, 2022). "In this study, GKT137831 inhibited AGE-induced EMP generation, indicating that the NOX-1/NOX-4 inhibitor could serve as a novel therapeutic target in AGE-related vascular endothelial injury." (PMID 29744367, 2018). "Furthermore, corilagin attenuated the protein levels of NOX1, NOX2, signal transducer and activator of transcription 3 (STAT3), and nuclear factor kappa B (NF-κB) in APAP-induced liver injury." (PMID 36829609, 2023).
non-small cell lung carcinoma (5 papers, 2015 to 2021). A group of at least three distinct histological types of lung cancer, including non-small cell squamous cell carcinoma, adenocarcinoma, and large cell carcinoma. "The use of NOX1 inhibitors can significantly reduce the ROS, lipid ROS and cell death of non-small cell lung cancer induced by erastin." (PMID 34418989, 2021). "In the LPS-stimulated non-small cell lung cancer (NSCLC) cells, ROS level was increased and significantly abolished by NOX1 inhibitor ML171." (PMID 34299310, 2021). "It is supposed that NOX1 could mediate the expression of C-X-C chemokine receptor type 4 (CXCR4) and Matrix metallopeptidase 9 (MMP9), which play an important role in the metastasis of non-small-cell lung carcinoma (NSCLC)." (PMID 34205998, 2021).
pancreatic cancer (5 papers, 2011 to 2022). "Further efforts are needed to clarify a possible association between NOX1 and NOX2 as prognostic biomarkers in pancreatic tumors." (PMID 35453444, 2022). "In this sense, the augmented detection of PARP-1, NOX1 observed in patients with pancreatic cancer who exhibited a lower survival in our study could be attributed to this fact." (PMID 35453444, 2022).
Parkinson disease (5 papers, 2014 to 2022). A progressive degenerative disorder of the central nervous system characterized by loss of dopamine producing neurons in the substantia nigra and the presence of Lewy bodies in the substantia nigra and locus coeruleus. "In the context of Parkinson’s disease, it has been shown to contribute to a ROS generating pathway acting with Nox1, causing neuronal death." (PMID 29267236, 2017). "In fact, upregulation of microglia NOX1 has been observed in a variety of neurological diseases, such as multiple sclerosis and Parkinson's disease." (PMID 36137346, 2022). "In support of a role of NOX1 in the pathology of Parkinson’s disease, NOX1 KO mice have a significant attenuation of DNA oxidative stress in a 6-OHDA striatal injection PD model." (PMID 28095923, 2017). "NADPH oxidase 1 (Nox1) and small GTPase Rac1, an important regulator in the Nox1 system, were found to accumulate in the dopaminergic neurons of patients with the Parkinson’s disease." (PMID 24926233, 2014).